GLI2 (GLI family zinc finger 2)
Diseases named in the same sentence as GLI2 in open-access papers (continued):
Sharing a sentence is not in itself a finding about the gene and the disease.
breast carcinoma (continued). "Other Hedgehog signaling factors like SHH, PTCH1, and GLI2 are overexpressed in breast cancer, but their connection to EMT is not well established in breast cancer." (PMID 31075939, 2019). "Previous studies have found that BCAR4 contributes to antiestrogen resistance and promotes breast cancer proliferation and metastasis through regulating noncanonical Hedgehog/GLI2 pathway." (PMID 30513511, 2018). "Additionally, WNT signaling regulates GLI2 during development and is involved in modulating the expression and functionality of the GLI proteins in several malignancies, including breast cancer." (PMID 27548161, 2016). "Studies on breast cancer metastasis to bone highlight the importance of PTHrP for regulation of bone destruction by a non-canonical Gli2-dependent mechanism through TGFβ signaling." (PMID 27738315, 2016). "Additionally, a pathway that may interact with Hedgehog signalling in breast cancer is TGF-β, which stimulates the upregulation of GLI1 and GLI2 transcription." (PMID 41301715, 2025). "Similarly, in an SNAI1-induced EMT model, EMT markedly upregulated representative YAP target genes, including AXL, CTGF, CYR61, and GLI2, in human breast carcinoma cells in media with or without serum." (PMID 40940864, 2025). "Interestingly, recent studies have shown that CUR inhibits the Hh pathway in several other cancers, such as breast cancer, gastric cancer, and medulloblastoma, by downregulating the expression of SHh, PTCH1, and GLI1/GLI2, leading to reduced cell proliferation, invasion, and migration." (PMID 39457084, 2024). "In the transgenic MMTV-ErbB2 (HER2-positive) mouse model, ΔNp63 supports breast cancer stemness by inducing the elevation of the SHH signaling cascade, inducing the expression of Smoothened (SMO), Protein Patched Homolog 1 (PTCH1), and GLI Family Zinc Finger 2(GLI2)." (PMID 35805056, 2022). "In addition, basal expression levels of GLI1 and GLI2, which are downstream of Hh ligands, are higher in TNBC than in HR+ breast cancer, suggesting that this pathway may be especially relevant to this sub-type." (PMID 31394751, 2019). "Finally, it was demonstrated that GLI2 can mediate non-canonical activation of HH signaling in breast cancer." (PMID 27548161, 2016). "Spearman correlation analysis of gene signatures in metastatic biopsies of breast cancer reveal a significant (p < 0.001) negative correlation between PTHLH and ITGA2 (p < 0.001), PTHLH and ITGB1 (p < 0.01), Gli2 and ITGA2 (p < 0.001), and Gli2 and ITGB1 (p < 0.0001)." (PMID 34199096, 2021).
medulloblastoma (53 papers, 2009 to 2025). A malignant, invasive embryonal neoplasm arising from the cerebellum. "For example, Prostaglandin E1 (PGE1) activates cAMP-PKA signaling via the EP4 receptor, promoting GLI2 ubiquitination and degradation to suppress Hedgehog signaling, overcoming GLI2 amplification-associated drug resistance in medulloblastoma models." (PMID 40370434, 2025). "A study showed that the upregulation of GLI2 was implicated in resistance to vismodegib in medulloblastoma, which is consistent with our data." (PMID 36553549, 2022). "In contrast, primary cilia of medulloblastoma and basal cell skin carcinoma caused by gain-of-function mutation of GLI2 increases the activity of GLI3 as a transcriptional repressor, resulting in suppression of the proliferation of these cancer cells." (PMID 32825105, 2020). "They showed that the cilia in the granule neuron precursors induced tumorogenesis in Smo-driven medulloblastoma, whereas cilia loss was required for medulloblastoma growth by constitutively active Gli2." (PMID 30884815, 2019). "Gli2 is an activator of the Hh pathway and plays a critical role in medulloblastoma tumorigenesis, with loss of Gli2 expression preventing the tumor formation." (PMID 29423837, 2018). "In our study, eight genetic variants, annotating three genes involved in the sonic hedgehog signaling pathway (CCND2, PTCH1, and GLI2), were indicted as associated with medulloblastoma risk." (PMID 26290144, 2015). "Eight genetic variants annotating three genes in the sonic hedgehog signaling pathway; CCND2, PTCH1, and GLI2, were found to be associated with the risk of medulloblastoma (Pcombined < 0.05)." (PMID 26290144, 2015). "GLI2 activation is also a key driver of SHH subset of medulloblastomas, which originate from granule cell progenitors." (PMID 37943875, 2023). "In the same manuscript authors showed that CK2 is required for HH signaling transduction and is critical for the stabilization and activity of GLI2 in medulloblastoma cells." (PMID 30934935, 2019). "A recent phosphoproteomic analysis identified the CK2 as a kinase critical for stabilization and activity of GLI2 and a promising therapeutic target in medulloblastoma." (PMID 30934935, 2019). "A key role in the coordination of the hedgehog homolog (HH) transcriptional program is mediated by the GLI2 zinc finger transcription factor; a recent study elucidated the GLI2 targets that promote medulloblastoma proliferation." (PMID 30279357, 2018). "Amplification of GLI1 and GLI2 loci has been detected in medulloblastoma, the most common malignant brain tumor in children." (PMID 30158435, 2018). "Atonal bHLH transcription factor 1 (ATOH1) directly regulates transcription of GLI2 in granule neuron precursors, the cell of origin of medulloblastoma, where it plays a critical role in tumorigenesis." (PMID 30158435, 2018). "For example, ciliary ablation has been shown to inhibit or to stimulate the progression of basal cell carcinomas and medulloblastomas driven by the Hedgehog pathway activator Smo, or the downstream Hedgehog pathway effector GLI2, respectively." (PMID 28178678, 2017). "Importantly, the combination of constitutively active GLI2 and loss of cilia led to the formation of medulloblastomas giving circumstantial evidence that the additional decreased amount of GLI3-R caused by ciliary absence might be necessary to induce oncogenesis." (PMID 27293550, 2016). "BRD4 inhibitor JQ1 or I-BET151 treatment inhibits GLI1 and GLI2 expression and growth of hedgehog-driven tumors in vitro and in vivo, such as basal cell carcinoma, medulloblastoma and atypical teratoid rhabdoid tumor." (PMID 26343727, 2015). "IHC showed less intense staining for the Shh-signaling target Gli2 in nodules of SmoA1 +;Pten +/− medulloblastomas." (PMID 20520772, 2010). "Notably, exons 10-11 skipping in Kif3a augmented human medulloblastoma cell proliferation by potentiating the transcriptional activity of Gli2." (PMID 40275081, 2025).
medulloblastoma (continued). "Also, abnormal expression of proteins downstream of this pathway (e.g., Smo, Gli1, Gli2, etc.)is importantly associated with the development of SHH-type medulloblastoma." (PMID 37821528, 2023). "Upon long-term treatment with LDE225, the RNA levels of the known SHH pathway genes Ptch1, Smo, Gli1, and Gli2 were equivalent to those in control-treated tumors in SD-CSC medulloblastomas, indicating continued activation of the SHH pathway consistent with acquired mutations in this pathway." (PMID 36688010, 2022). "The overexpression of this protein sustains clonogenic growth, migration and tumorigenicity of medulloblastoma cells, and recently it was demonstrated to interact with GLI1 and GLI2 proteins stimulating the trans-activation of the Sonic Hedgehog pathway in medulloblastoma." (PMID 34445164, 2021). "Finally, recent studies have revealed that the bHLH TF Atoh1 synergizes with Gli2 to activate a medulloblastoma transcriptional network." (PMID 33006313, 2020). "Additionally, these modules were interconnected via several hub genes, namely, FGFR1, BMP4, PAX6, PAX3, SOX9, and GLI2, all of which have been related to medulloblastomas in previous studies." (PMID 32508873, 2020). "Also, Vismodegib- or NVP-LDE225- (SMO/SHH pathway inhibitors) resistant BCCs patients and mouse medulloblastoma cells have been shown to acquire mutations in SUFU or amplification of a downstream transcriptional effector of the SHH signaling pathway, GLI2." (PMID 27608848, 2016). "Arsenic trioxide, which targets GLI2 for degradation, inhibits the growth of Vismodegib-resistant medulloblastoma in vivo, and the combination of arsenic trioxide and itraconazole, a SMO inhibitor, shows greater anti-tumor efficacy in vivo than either agent alone." (PMID 27608848, 2016). "In particular, human medulloblastomas of the SHH subgroup, accounting for ~30% of all medulloblastomas, arise mostly due to mutations in the PTCH1 receptor, the transmembrane activator Smoothened, the signal transduction modulator SUFU and transcriptional regulator GLI2." (PMID 25901736, 2015). "Interestingly, the fraction of M2 macrophages in Group 4 medulloblastoma were positively correlated with the risk score and were significantly correlated with the expression level of four signature genes (CCNY, SYNE3, CYB5D2, and SELENOV) and four hub genes (GLI2, PAX6, RUNX2, and ZIC1)." (PMID 32508873, 2020). "Brd4 controls expression of the medulloblastoma essential gene MYC in G3 medulloblastomas, which have poor prognosis as well as GLI1 and GLI2 levels in Sonic hedgehog (SHH)-driven medulloblastomas, which have intermediate prognosis." (PMID 31292434, 2019). "GLI2 and GLI3 are two of the principle mediators of the sonic hedgehog signaling pathway (Shh) and are upregulated in SHH-medulloblastomas (SHH-MB) relative to normal brain samples." (PMID 29099739, 2017). "BCOR suppresses the tumor progression of SHH medulloblastoma by a BCL6/BCOR/SIRT1 complex that induces epigenetic repression of GLI1 and GLI2." (PMID 27825128, 2016). "Two studies have reported amplifications of chromosomal regions containing GLI2 in Vismodegib and NVP-LDE-225-resistant medulloblastoma cell lines." (PMID 24287465, 2013). "Compared with other tumor and normal cells, the ecDNA+ cell cluster also overexpressed GLI2 (q < 0.001), a mediator of SHH-mediated transcription and marker for SHH medulloblastoma, despite GLI2 not being affected by copy number alteration in this tumor." (PMID 37945900, 2023). "Furthermore, analysis of patient samples revealed an enrichment of several hedgehog pathway genes, such as GLI2, GLI3 and HHIP in cells from medulloblastoma patients expressing high SCARB1 levels." (PMID 29352211, 2018). "In this brief report, following an analysis of microarrays of medulloblastoma patients, we identify key proteins—such as LSD1, EZH2, GLI2, GLI3, and PTK7—that may serve as drug targets." (PMID 29099739, 2017).
medulloblastoma (continued). "In case of basal cell carcinoma development, constitutively active GLI2 was sufficient to induce carcinogenesis, while, in case of medulloblastoma development, constitutively active GLI2 did not give rise to carcinogenesis." (PMID 27293550, 2016). "Interestingly, SOX9 might function upstream of GLI2, which is known to be a major effector in the Hedgehog signaling, and act as a key driver of SHH medulloblastomas." (PMID 32508873, 2020). "Furthermore, we identified overexpression of GLI2 and SMO as a signature of resistance to smoothened inhibition in melanoma, as has been reported recently in human medulloblastoma using both NVP-LDE-225 and Vismodegib, an oral SMO inhibitor that is FDA-approved in advanced basal cell carcinoma." (PMID 24287465, 2013). "Moreover, activated NK cells were positively correlated with GLI2 (p = 0.020, r = 0.318) and ELAVL3 (p = 0.020, r = 0.317) expression, and resting mastocyte cells were significantly correlated with CACNA2D1 expression (p = 0.026, r = 0.303) in SHH medulloblastomas." (PMID 32508873, 2020). "SHH mediators GLI2 and GLI3 are significantly upregulated in SHH-MB, but GLI3 is not upregulated in the larger pool of medulloblastomas, and there is only weak evidence that GLI2 is upregulated." (PMID 29099739, 2017). "In addition, ATOH1, GLI2, and SOX1 protein levels were significantly reduced in SI-CSC medulloblastomas but not in SD-CSC medulloblastomas that were resistant to LDE225." (PMID 36688010, 2022).
melanoma (40 papers, 2013 to 2026). A malignant, usually aggressive tumor composed of atypical, neoplastic melanocytes. "GLI2 upregulation in melanoma was also associated with mesenchymal transition, which promotes cell-cell adhesion and the other motile behavior and is typically associated with poor prognosis." (PMID 40719625, 2025). "The targeting by TFs (see the sections “Methods”: “Applications of netZoo using the Cancer Cell Line Encyclopedia”) glioma-associated oncogenes 1 and 2 (GLI1 and GLI2) was also significantly increased in melanoma." (PMID 36894939, 2023). "Other downstream counterparts of Hh signaling pathway such as Gli-2 and Gli-3 have been associated with melanoma as well." (PMID 28212537, 2017). "Using 1205Lu melanoma cells that express high levels of Gli2, the authors showed that loss of Gli2 using shRNA led to a decreased incidence of bone metastases as well as smaller lesions." (PMID 26343726, 2015). "Moreover, higher levels of Gli2 are associated with a loss of the cell adhesion molecule E-cadherin in melanoma cell lines with increased capacity for local invasion; higher levels correlated with the most aggressive tumors." (PMID 29423837, 2018). "We observed reduced PTCH1 and SUFU repressors expression and GLI2 upregulation as common melanoma features." (PMID 41596411, 2026). "Another group reported a direct correlation between the expression of GLI2, the release of metalloproteinases and the propensity to form melanoma bone metastasis in mice, as well as an inverse correlation with E-cadherin expression." (PMID 41596411, 2026). "Gene expression profiling revealed downregulation of two repressors, PTCH1 and SUFU, along with upregulation of the downstream effector GLI2 in melanoma cells compared to normal melanocytes." (PMID 41596411, 2026). "Consistently, in melanoma cell lines carrying BRAF or NRAS mutation, GLI2 expression was stronger than in wild-type cells." (PMID 41596411, 2026). "All together, these results indicate that the MEK5/ERK5 pathway positively modulates GLI1 and GLI2 transcription factors both at transcriptional and protein levels in melanoma cells." (PMID 39998753, 2025). "Here, we analyzed surgically resected oral malignant melanoma specimens and observed that Sonic Hedgehog, Gli1, and Gli2 were highly expressed in tumor cells, vasculatures, and osteoclasts." (PMID 37240209, 2023). "The normal skin tissues showed few of these positive cells, and the number of SHH-, Gli1-, and Gli2-positive cells per mm2 was significantly higher in the melanoma tissues than in the normal skin tissues (p < 0.05)." (PMID 37240209, 2023). "In contrast, expression of Shh pathway components (Gli-1, Gli-2, and Ptch-1) in the nevi from P4 and P5 and melanoma markers (c-kit, MAGE, and CDK4) in the nevus from P1 was markedly increased." (PMID 33509032, 2021). "For example, Gli1 and Gli2 are transcriptional targets of Transforming Growth-Factor-β/Smad3 in melanoma." (PMID 33228057, 2020). "High GLI2 expression in invasive melanoma cells depends largely upon autocrine TGF-β signaling and is associated with a mesenchymal transition and loss of E-cadherin expression, events associated with enhanced cell motility and capacity to metastasize." (PMID 32879407, 2020). "Knockdown of Gli2 restored sensitivity to vemurafenib-resistant melanoma cells while TWIST1, which is overexpressed in colon cancer, plays a crucial role in the resistance of these tumors to irinotecan." (PMID 30167084, 2018). "We find that itraconazole increases Gli-3, Axin-1 expression but decreases Gli-1, Gli-2, Axin-1, β-catenin, Wnt3A and Cyclin D1 expression in both melanoma cell lines when compared with untreated cells." (PMID 28212537, 2017). "Recently, GLI2, a TGF-β target has been implicated in increased melanoma invasion and metastatic capacity." (PMID 27172792, 2016).